C6orf89 (chromosome 6 open reading frame 89)
Description:
Exhibits histone deacetylase (HDAC) enhancer properties. May play a role in cell cycle progression and wound repair of bronchial epithelial cells.
Synonyms: BRAP; FLJ25357; PS1TP5TP1
Tractability: Antibody: its Gene Ontology location is reachable by antibodies, with high confidence; UniProt predicts a signal peptide or a membrane-spanning region. PROTAC: ubiquitination databases record sites on it.
Gene: Protein-coding gene on chromosome 6 (36,871,870 to 36,928,964, forward strand). Ensembl gene ENSG00000198663.
Subcellular location: Golgi apparatus membrane (Isoform 1); Midbody; Golgi apparatus membrane (Isoform 2); Cytoplasm (Isoform 3); Nucleus, nucleolus
Gene Ontology:
Molecular function: protein binding
Biological process: chromatin remodeling; epithelial cell proliferation; positive regulation of cell cycle; wound healing
Cellular component: cytoplasm; Golgi membrane; midbody; plasma membrane; nucleolus
Genetic constraint (gnomAD): Loss-of-function variants: 27 observed, 41.69 expected, observed/expected ratio (o/e) 0.65, 90% interval 0.48 to 0.89. The upper end of that interval is the gene's LOEUF score, 0.89, which puts it in group 3 of 6, group 1 being the genes least tolerant of losing a copy. Missense variants: 387 observed, 448.22 expected, observed/expected ratio (o/e) 0.86, 90% interval 0.79 to 0.94. Synonymous variants: 163 observed, 158.16 expected, observed/expected ratio (o/e) 1.03, 90% interval 0.91 to 1.17.
Homologues: Orthologues: chimpanzee C6H6orf89 (99% identical), macaque C4H6orf89 (94% identical), dog C6orf89 (87% identical), pig C6orf89 (87% identical), rat C20h6orf89 (84% identical), mouse BC004004 (84% identical), guinea pig C6orf89 (75% identical), zebrafish zgc:162255 (27% identical).
Diseases named in the same sentence as C6orf89 in open-access papers:
C6orf89 is named in the same sentence as 2 diseases in open-access papers, as found by Europe PMC text mining. Sharing a sentence is not in itself a finding about the gene and the disease. The quoted sentences say what the papers report.
psoriasis (1 paper, 2024). An autoimmune condition characterized by red, well-delineated plaques with silvery scales that are usually on the extensor surfaces and scalp. "Our group found that human bombesin-receptor activated protein (BRAP), encoded by C6orf89 gene, was expressed in keratinocytes of normal skin and lesions of psoriasis." (PMID 38169666, 2024).
C6orf89 also shares sentences with these, for which no sentence is quoted: cancer (1 paper).